AR (androgen receptor)
Diseases named in the same sentence as AR in open-access papers (continued):
Sharing a sentence is not in itself a finding about the gene and the disease.
prostate carcinoma (continued). "We have previously demonstrated that checkpoint kinase 2 (CHK2) is a critical negative regulator of androgen receptor (AR) transcriptional activity, prostate cancer (PCa) cell growth, and androgen sensitivity." (PMID 32579110, 2020). "In normal prostate epithelium, the AR suppresses proliferation and promotes differentiation; however, during carcinogenesis prostate cancer cells develop “lineage-addiction,” where the AR promotes tumor progression." (PMID 33134178, 2020). "We previously performed AR ChIP-seq to map the genome-wide occupancy of AR in prostate cancer cells." (PMID 32704143, 2020). "FUS promoted conditions that favored cell-cycle arrest by reducing proliferator factors and was a key link between androgen receptor signaling and the progression of the cell cycle in prostate cancer." (PMID 32117463, 2020). "The previous meta-analysis on prostate cancer was carried out deciphering the role of miRNAs targeting the androgen receptor." (PMID 32397507, 2020). "The research conducted in prostate cancer (PC) suggested that CNPY2 promoted cell growth of PC cells by inhibition of androgen receptor (AR) protein degradation through MYLIP-mediated AR ubiquitination." (PMID 32039833, 2020). "AR activation in the stroma has been shown to be essential for prostate cancer progression and metastasis." (PMID 33062889, 2020). "In prostate cancer AR target genes are suppressed by Cyclin D1, which limits, in such a way, the AR activity induced by its specific ligands." (PMID 33317149, 2020). "The term aggressive variant prostate cancer (AVPCa) refers to androgen receptor (AR)-independent anaplastic forms of prostate cancer (PCa), clinically characterized by a rapidly progressive disease course." (PMID 32344931, 2020). "Androgen receptor (AR) activated by DHEA or other types of androgen was reported to promote drug resistance in prostate cancer." (PMID 31896509, 2020). "In summary, brassicasterol from edible aquacultural H. abdominalis exerts an anti-cancer effect by dual-targeting AKT and AR signaling in prostate cancer." (PMID 32972001, 2020). "Several phase 2 clinical trials have been conducted to test the clinical efficacy of multiple FDA-approved AR inhibitors for AR-positive prostate cancer as a possible treatment for AR-positive TNBC." (PMID 32846967, 2020). "Intrinsic CXCL8 signalling underpins prostate cancer cell survival through the activation of AR, HIF-1 and NF-κB transcription factors, and increases expression of anti-apoptotic proteins, including members of the Bcl family." (PMID 32743555, 2020). "AR signaling is a definitely therapeutic target, especially for hormone-related cancer, such as prostate cancer." (PMID 32489450, 2020). "Functional interplay between AR and NF-κB signals has been documented in, for instance, prostate cancer cells." (PMID 32759680, 2020). "Specifically in prostate cancer (PC) cell plasticity allows cancer cells to reprogram and survive despite androgen receptor (AR) inhibition, being considered one of the mechanisms involved in androgen deprivation therapy (ADT) resistance." (PMID 33224888, 2020). "Based on the crucial role played by androgens and AR, hormonal therapy is one type of treatment available for prostate cancer, and the second-generation antiandrogen enzalutamide has been approved for castration-resistant prostate cancer." (PMID 32102219, 2020). "AR signaling, especially the AR variant AR3/AR-V7-driven molecular events, are critical for therapeutic resistance in aggressive prostate cancer." (PMID 32354165, 2020). "In contrast, AR is an emerging biomarker for prostate cancers, salivary duct carcinomas, and breast cancers." (PMID 32867793, 2020). "In prostate cancer cell models, decorin prevents androgen receptor nuclear translocation and inhibits the production of PSA." (PMID 32056047, 2020). "Androgen deprivation therapy (ADT), which inhibits transcriptional activity of AR, is utilized in the treatment of advanced prostate cancer." (PMID 35582225, 2020).
prostate carcinoma (continued). "Though the exact role of AR in the development of prostate cancer is uncertain, androgen ablation therapies have been associated with triggering cell death or cell cycle arrest of prostate cancer cells." (PMID 33240734, 2020). "A number of DNA damage response genes have previously been reported to be controlled by AR expression in prostate cancer models, including XRCC2, XRCC3, and PRKDC." (PMID 32117061, 2020). "Common targets down-regulated in NE-like prostate tumors included LDHA, already described in prostate cancer cells and activated by AR." (PMID 32041153, 2020). "In conclusion, our data suggest that, despite differences in available AR-targeted therapies, castration-resistant prostate cancer cells develop a shared metabolic phenotype in response to AR inhibition." (PMID 32427840, 2020). "The panel generated from this approach identified as top candidates mutations in known driver genes (e.g. HRAS) and prostate cancer related transcription factor binding sites (e.g. MYC, AR)." (PMID 32859160, 2020). "Our studies demonstrate that HOXC4 and HOXC6 co-localize with HOXB13, FOXA1 and AR, three transcription factors previously shown to contribute to the development of prostate cancer." (PMID 32012197, 2020). "Previous studies have demonstrated the AR acts as a licensing factor in DNA replication in androgen sensitive prostate cancer cells and that androgens induce double-strand DNA breaks within prostate cancer cell lines." (PMID 32002120, 2020). "Another AR degrader ARD-69 has DC50 values of <1 nM in prostate cancer cell lines LNCaP and VCaP (DC50: the concentration at which 50% of the target protein has been degraded)." (PMID 32983997, 2020). "In an initial study, KLF5 was revealed to be a target of AR and to promote cancer progression in prostate cancer." (PMID 32943987, 2020). "All prostate cancer cases characteristically expressed ERa on the apical membrane of the AR+ epithelium." (PMID 33266334, 2020). "In summary, these data strongly support the role for GR inhibition in patients and demonstrate the efficacy of mifepristone in suppressing the growth of AR-null, GR-expressing prostate cancer cells in vitro." (PMID 33303959, 2020). "Overall, both the AR and Tip60 are master metabolic regulators that mediate cellular energy metabolism in prostate cancer, providing a framework for the development of novel therapeutic targets in androgen-dependent prostate cancer." (PMID 32927797, 2020). "Combination therapies using ralaniten with ionizing radiation were evaluated for effects on proliferation, colony formation, cell cycle, DNA damage, and Western blot analyses in human prostate cancer cells that express both full-length AR and AR-Vs." (PMID 32708219, 2020). "Since AR plays a pivotal role in prostate cancer and MNK/eIF4E pathway is involved in cancer resistance and progression, dual AR/MNK inhibition seems to be a promising PCa therapy." (PMID 32340135, 2020). "Among them include, phenyl ITCs that inhibit transcriptional activity regulated by androgen receptor modulating growth of prostate cancer cells through down-regulation of an androgen receptor-regulated gene." (PMID 32806771, 2020). "Efforts to improve outcomes for these patients have revealed that the androgen receptor (AR) regulates DNA damage repair (DDR) in prostate cancer." (PMID 32708219, 2020). "Studies focused on dissecting the mechanisms of AR-centred prostate cancer development reveal that AR not only regulates gene expression but also regulates higher-order chromatin configuration." (PMID 32634370, 2020). "Similar transdifferentiation was observed in prostate cancer dependent on androgen receptor (AR)-mediated signalling." (PMID 32595946, 2020). "In fact, genomic alterations in c-MYC, FOXO1 or the androgen receptor (AR) have been described in neuroblastoma, breast or prostate cancer, respectively." (PMID 32933565, 2020).
prostate carcinoma (continued). "The lncRNA HOTAIR increases the androgen receptor-mediated transcriptional program and promotes the growth of castration-resistant prostate cancer." (PMID 32117463, 2020). "Androgen Deprivation therapy (ADT) using anti-androgens such as Enzalutamide and Abiraterone is commonly used to target and inhibit AR signaling for therapeutic purposes in prostate cancer." (PMID 32645914, 2020). "Next, we validated the regulation of 21 lncRNAs by androgen and AR in prostate cancer cells by quantitative reverse transcriptase polymerase chain reaction (qRT-PCR)." (PMID 32704143, 2020). "After first-line androgen-deprivation therapy, prostate cancer patients are treated with androgen receptor antagonists such as enzalutamide to inhibit androgen-dependent prostate cancer cell growth." (PMID 32802517, 2020). "Radiotherapy has been shown to induce AR expression in prostate cancer cells, and ADT sensitizes cancer cells to radiotherapy." (PMID 33062889, 2020). "For instance, SMYD3 directly targets the androgen receptor and telomerase gene, thereby promoting development and progression of prostate cancer and other human malignancies." (PMID 32007952, 2020). "Early-stage prostate cancer is heavily dependent on AR activation for survival, but reoccurrence is in most cases, characterized by androgen-independent tumors due to adaptations to low androgen levels." (PMID 33182828, 2020). "AR deprivation therapy, well-known in prostatic cancer, has been proposed for FBC and MBC with varying results." (PMID 32626651, 2020). "Preliminary clinical research using AR-targeted drugs, which have already been FDA-approved for prostate cancer (PC), has given promising results for AR-positive breast cancer patients." (PMID 31952272, 2020). "The synergy of Notch inhibition and ADT has been demonstrated in ERG-driven prostate cancer in combination with both AR antagonists such as enzalutamide and inhibitors of androgen synthesis such as abiraterone." (PMID 32575680, 2020). "The prostate cancer epithelium also express nuclear AR but co-expressed ERa at the apical pole in each cell." (PMID 33266334, 2020). "This suggests that an overexpression of Tip60 with increased nuclear localization contributes to AR activation in an androgen-independent manner, thus promoting the transition of an androgen-responsive stage to castrate-resistant prostate cancer." (PMID 32927797, 2020). "IL-23 secreted by myeloid cells drives castration-resistant prostate cancer by activating the androgen receptor pathway, promoting cell survival and proliferation in androgen-deprived conditions." (PMID 31937346, 2020). "What is the association between androgen receptor inhibitor (ARI) therapy and risk of fall and fracture in men with prostate cancer?" (PMID 33201234, 2020). "Here we compared the sets of AR downstream signals in prostate cancer cells identified by RNA-seq with those obtained as CRPC-related lncRNAs." (PMID 32704143, 2020). "Substrates of ABCC4 include DHEA-S, and the expression of ABCC4 in primary prostate cancer tissue was reported to be reduced upon androgen ablation, suggesting a role for AR in regulating expression of ABCC4." (PMID 32584883, 2020). "Isoform PMEPA1-e was androgen responsive, consistent with the observations that PMEPA1-e was only detectable in AR positive prostate cancer cells." (PMID 32064040, 2020). "Our work provides evidence for a new mechanism by which AR alters the transcriptome of prostate cancer cells by modulating alternative splicing." (PMID 32820253, 2020). "Although its role has been studied extensively in prostate cancer, growing evidence suggests AR plays a role in other cancers, including colon, breast, and bladder." (PMID 32847068, 2020). "A previous report demonstrated consistently that increased infiltration of Pref-1 and CD29 positive preadipocytes promote prostate cancer metastasis via the mR301a/AR/TGFβ1/Smad/MMP9 pathway." (PMID 32971847, 2020).
prostate carcinoma (continued). "Neuroendocrine prostate cancer (NEPC) can arise de novo, but much more commonly occurs as a consequence of a selective pressure from androgen deprivation therapy or androgen receptor antagonists used for prostate cancer (PCa) treatment." (PMID 32041153, 2020). "Another study that aims to probe the genomic landscape used liquid biopsies and circulating tumor DNA (ctDNA) obtained from prostate cancer patients and identified that AR amplification results in less responsive to antiandrogens." (PMID 35582225, 2020). "AR antagonist enzalutamide is generally used for prostate cancer and is now under clinical trials for kidney cancer patients." (PMID 32847068, 2020). "Previously we demonstrated that CYP3A5 facilitates nuclear translocation of androgen receptor in prostate cancer cells." (PMID 32316460, 2020). "Together, these results demonstrate the significance of ERRα-mediated up-regulation of AKR1C3 in the activation of AR signaling in prostate cancer cells through the enzymatic role of AKR1C3 in the backdoor pathway of androgen biosynthesis." (PMID 32226548, 2020). "Although the epigenetic regulation of AR has been extensively studied in prostate cancer, a growing body of evidence has suggested a role for AR in other cancers, including colon, breast, and bladder cancer." (PMID 32781788, 2020). "The first FDHT-PET imaging of AR in men with advanced prostate cancer was published together with my colleagues at Washington University Medical School and nearly simultaneously by investigators at Sloan Kettering Cancer Center." (PMID 32718075, 2020). "Reciprocal feedback inhibition of AR by PI3K signaling in prostatic cancer has been reported, with the inhibition of PI3K leading to the derepression and activation of AR target genes, and the inhibition of AR leading to reciprocal PI3K pathway activation." (PMID 32042320, 2020). "Our analysis in prostate cancer cell lines shows that modulation of AR signaling dysregulates splicing of functionally relevant genes." (PMID 32820253, 2020). "Specifically, 47 out of 119 cassette exon events occurring upon LNA-mediated DSCAM-AS1 silencing were observed also upon siRNA-mediated silencing of hnRNPL in LNCaP, an androgen receptor-positive prostate cancer cell line." (PMID 32503257, 2020). "Androgen receptor signaling was reported as one of the significant signaling pathways that contributes to prostate cancer development." (PMID 32854238, 2020). "For instance, lncRNAs PCAT8 and PCGEM1 are highly overexpressed in aggressive prostate cancer and strongly enhance androgen-receptor-mediated gene activation and proliferation in prostate cancer cells." (PMID 32849794, 2020). "For a more extensive description of the role of androgens/AR in human cancer besides prostate cancer we refer the reader to comprehensive reviews of this field." (PMID 32714315, 2020). "Failure to respond to AR-centered therapy and development of castration-resistant prostate cancer (CRPC) is associated with diverse molecular mechanisms applied by prostate cancer cells." (PMID 32645914, 2020). "A recent study further elaborated on the cross-talk between DNA-PKcs and the AR, and highlighted the potential of combining respective inhibitors in patient-derived prostate cancer explants." (PMID 33158305, 2020). "The objective of the study was to study the PR expression in patients with benign prostatic hyperplasia and prostate cancers in connection with the transcription, growth factors, AR, ERα, ERβ, and components of the AKT/mTOR signaling pathway expression." (PMID 32102520, 2020). "Indeed, prostate cancer cells with heterogenous expression of AR and other nuclear receptors, as well as their associated cofactors that may differ drastically between each other, could eventually mask the activity of potential hits, and may not be the most pertinent models." (PMID 32560058, 2020).
prostate carcinoma (continued). "Anti-androgen therapies have been effective at inhibiting the growth of AR+ prostate cancer cells due to their reliance on AR signaling." (PMID 32117061, 2020). "SIRT1 inhibited AR-dependent prostate cancer cell growth and induced endogenous AR target genes repression while SIRT1 antagonists induced expression of AR-responsive target genes (AR) both in vivo and in vitro." (PMID 33330467, 2020). "The critical driving force for prostate cancer is the androgen receptor (AR)-regulated gene expression that is initiated by the binding of androgen to AR." (PMID 32456317, 2020). "PET imaging of AR in men with advanced prostate cancer was published in 2004 and 2005 by me and my colleagues at Washington University Medical School in St." (PMID 32718075, 2020). "For example, lncRNA LBCS suppressed the castration resistance and proliferation of prostate cancer cells by functioning as a scaffold of hnRNPK protein and AR mRNA to inhibit AR translation efficiency." (PMID 32351538, 2020). "Beyond silencing gene expression via its histone methyltransferase activity, EZH2 can directly coactivate the androgen receptor and other transcription factors in prostate cancer." (PMID 32143573, 2020). "In the primary prostate cancer, the expression of this gene correlated with AR pathway and luminal markers." (PMID 32375698, 2020). "Another piece of the puzzle that is missing in terms of understanding the role of HDACs in prostate cancer is the involvement of the AR." (PMID 32019149, 2020). "In prostate cancer study, IL-23 produced by myeloid-derived suppressor cells (MDSCs) and can activate the androgen receptor pathway in promoting cell survival and proliferation." (PMID 31937346, 2020). "MYSM1 was originally characterized as an epigenetic regulator that promotes the expression of androgen receptor target genes in prostate cancer cell lines, through deubiquitination of histone H2AK119ub." (PMID 32344625, 2020). "It will be interesting to determine in future work if the AR indirect up-regulation of Twist1 via ETV1 is involved in these other steps of prostate cancer metastasis." (PMID 32296610, 2020). "Several studies have shown that AR signaling alters anabolic and catabolic metabolism in prostate cancer cell lines." (PMID 32927797, 2020). "In the context of prostate cancer (PCa), the androgen receptor (AR) has many oncogenic functions such as increasing the proliferation and survival of cancer cells." (PMID 32132580, 2020). "Although less thoroughly investigated than the three receptors, ER, PgR, and AR, discussed here in detail, GR and MR certainly play roles in various cancers, including breast and possibly prostate cancers." (PMID 32718075, 2020). "MIL-38 was reported to react with both prostate cancer tissue and prostate cancer cell lines, including androgen receptor null cell lines DU-145 and PC-3, and with less binding to androgen-sensitive LNCaP cells." (PMID 32382920, 2020). "The role of androgen receptor (AR) in prostate cancer is well established and AR targeted drugs are currently part of the standard care positively affecting the course and outcome of the disease." (PMID 32374753, 2020). "AR and its downstream signaling drive progression of both localized and advanced metastatic prostate cancer, making androgen deprivation therapy (ADT) the main initial treatment for patients with advanced PCa." (PMID 32477465, 2020). "This is because the AR expression level of the cell lines that we used was notably lower than that of prostate cancer, and the repressive effect on neoplasia was relatively strong." (PMID 32781788, 2020). "In urological cancers, HOTAIR overexpression is able to increase prostate cancer cells growth and invasion by binding androgen receptor (AR) protein and blocking its degradation." (PMID 32397382, 2020). "The combination of RT and the first generation AR blockers to improve the outcome in prostate cancer remain a matter of controversial debate in clinical trials." (PMID 32878283, 2020).